ADISSP (adipose secreted signaling protein)
Description:
Adipocyte-secreted protein (adipokine) that acts as a key regulator for white adipose tissue (WAT) thermogenesis and glucose homeostasis at least in part through activation of protein kinase A (PKA).
Synonyms: C20orf27; FLJ20550
Tractability: Antibody: UniProt places it where antibodies can reach, with medium confidence; its Gene Ontology location is reachable by antibodies, with medium confidence. PROTAC: ubiquitination databases record sites on it.
Gene: Protein-coding gene on chromosome 20 (3,753,505 to 3,768,738, reverse strand). Ensembl gene ENSG00000101220.
Subcellular location: Secreted
Subcellular location (Human Protein Atlas): Cytosol; Nucleoplasm; Predicted to be secreted
Gene Ontology:
Molecular function: protein phosphatase 1 binding
Biological process: positive regulation of non-canonical NF-kappaB signal transduction; positive regulation of transforming growth factor beta receptor signaling pathway; adaptive thermogenesis; adenylate cyclase-activating G protein-coupled receptor signaling pathway; glucose homeostasis
Cellular component: extracellular region
Genetic constraint (gnomAD): Loss-of-function variants: 11 observed, 17.42 expected, observed/expected ratio (o/e) 0.63, 90% interval 0.4 to 1.04. The upper end of that interval is the gene's LOEUF score, 1.04, which puts it in group 4 of 6, group 1 being the genes least tolerant of losing a copy. Missense variants: 189 observed, 246.92 expected, observed/expected ratio (o/e) 0.77, 90% interval 0.68 to 0.86. Synonymous variants: 100 observed, 103.81 expected, observed/expected ratio (o/e) 0.96, 90% interval 0.82 to 1.14.
Homologues: Orthologues: chimpanzee ADISSP (99% identical), macaque ADISSP (98% identical), dog ADISSP (97% identical), guinea pig ADISSP (95% identical), pig ADISSP (95% identical), mouse Adissp (90% identical), rat Adissp (78% identical), zebrafish ADISSP (61% identical), tropical clawed frog adissp (56% identical), zebrafish adissp (41% identical), Drosophila melanogaster CG6983 (32% identical).
Diseases named in the same sentence as ADISSP in open-access papers:
ADISSP is named in the same sentence as 4 diseases in open-access papers, as found by Europe PMC text mining. Sharing a sentence is not in itself a finding about the gene and the disease.
ADISSP shares sentences with these, for which no sentence is quoted: colorectal cancer (2 papers); tumor (2); leukemia (1); Obesity (1).